PPP2R2B (protein phosphatase 2 regulatory subunit Bbeta)
Diseases named in the same sentence as PPP2R2B in open-access papers (continued):
Sharing a sentence is not in itself a finding about the gene and the disease.
bladder cancer (2 papers, 2024). "However, the molecular mechanism underlying the role of PPP2R2B in bladder cancer and platinum resistance remain largely unknown." (PMID 38976080, 2024). "Recently, PPP2R2B has been reported to inhibit bladder cancer progression and serve as a possible biomarker for platinum resistance." (PMID 38976080, 2024). "This reflected the significant effect of PPP2R2B expression level on the efficacy of chemotherapy in bladder cancer." (PMID 38976080, 2024). "This study illuminates the potential of PPP2R2B expression as a novel and valuable predictive biomarker for individuals grappling with bladder cancer, offering clinicians a robust tool for prognostic evaluation and personalized treatment strategies." (PMID 38409085, 2024).
depression (2 papers, 2019 to 2025). "Whereas previous studies observed decreased activation of adenylate cyclase and PKA in depression, in this study, we found a significant decrease of PPP1R13B and PPP2R2B, two phosphate family proteins that counterbalance the action of PKA, in the hippocampus." (PMID 30983951, 2019).
glioma (2 papers, 2016 to 2020). A benign or malignant brain and spinal cord tumor that arises from glial cells (astrocytes, oligodendrocytes, ependymal cells). "Beside the genes, which were described earlier as possible targets of epigenetic silencing in gliomas (SFRP1, SFRP2, DKK1), the methylation of PPP2R2B, SOX17, and DACH1 was also assessed." (PMID 26337424, 2016). "The methylation of SFRP1, SFRP2, PPP2R2B, DKK1, SOX17, and DACH1 was analyzed in 64 glioma samples using methylation-specific polymerase chain reaction (MSP)." (PMID 26337424, 2016).
hepatocellular carcinoma (2 papers, 2017 to 2024). A malignant tumor that arises from hepatocytes. "Repression of PPP2R2B and other components of PP2A complex by CRL4B complex have been reported in our previous work on hepatocellular carcinoma and myeloid derived suppressive cells (MDSCs), suggesting PP2A as a common downstream target of CRL4B in different biological processes." (PMID 38331954, 2024). "In human gastric cancer, EZH2 promotes the activation of Wnt/β-catenin signaling by down-regulating CXXC4 expression, and several other Wnt pathway antagonists, including NKD1, PRICKLE1, PPP2R2B, AXIN2 and SFRP5, were concordantly silenced by EZH2 in hepatocellular carcinomas." (PMID 27926488, 2017).
amyloid (1 paper, 2020). "The PPP2R2B association remained genome-wide significant after additionally covarying for global amyloid burden and cerebrovascular disease risk, while the IGF2BP3 association was partially attenuated after accounting for amyloid load." (PMID 33426524, 2020).
Atrophy (1 paper, 2024). Any weakening or degeneration, especially through lack of use. "Expansion of CAG repeats in PPP2R2B gene has been associated with autosomal dominant spinocerebellar ataxia 12, characterized by diffuse cerebral and cerebellar atrophy." (PMID 38331954, 2024).
autoimmune disease (1 paper, 2021). A disorder resulting from loss of function or tissue destruction of an organ or multiple organs, arising from humoral or cellular immune responses of the individual to their own tissue constituents. "Hyper-methylation of PPP2R2B induced acquired apoptosis deficiency and contribute to autoimmune diseases." (PMID 33407498, 2021).
Cerebellar atrophy (1 paper, 2022). Cerebellar atrophy is defined as a cerebellum with initially normal structures, in a posterior fossa with normal size, which displays enlarged fissures (interfolial spaces) in comparison to the foliae secondary to loss of tissue. "The MRI brain showed severe cerebellar atrophy with a CAG repeat length was 40 in PPP2R2B gene." (PMID 35531119, 2022).
Chagas disease (1 paper, 2020). A parasitic infection caused by Trypanosoma cruzi. "Among the pathways relevant to dopaminergic synapse, sphingolipid signaling, and Chagas disease, transcript abundance of the beta isoform of regulatory subunit 55 of protein phosphatase 2A (PPP2R2B) was decreased 1.2-fold in moderate WS relative to mild samples." (PMID 32612536, 2020).
colorectal tumor (1 paper, 2014). "Specifically, epigenetic loss of Protein phosphatase 2, regulatory subunit B, beta (PPP2R2B), occurring in >90% colorectal tumor samples, was indicated as a molecular event affecting the sensitivity of CRC to mTOR inhibitors." (PMID 24393708, 2014).
Corneal astigmatism (1 paper, 2023). "By using a GWAS approach, SNPs near TJP2, PCBP3, CADM2, and TRPM3 were identified to be associated with myopia or refractive errors, and HMG20A and PPP2R2B were associated with axial length and corneal astigmatism, respectively." (PMID 37449273, 2023).
diabetes (1 paper, 2022). "Simulated diabetes augmented and reduced the protein levels of PPP2R2B and YWHAB in BCAEC, respectively, which suggest impaired insulin signaling in our model." (PMID 35835939, 2022).
epilepsy (1 paper, 2022). A brain disorder characterized by episodes of abnormally increased neuronal discharge resulting in transient episodes of sensory or motor neurological dysfunction, or psychic dysfunction. "We have previously shown that PPP2R2B as a subunit of protein phosphatase 2A had a decreased expression in brain injury animals (TBI model and three epilepsy models)." (PMID 36846021, 2022).
leukemia (1 paper, 2022). A malignant (clonal) hematologic disorder, involving hematopoietic stem cells and characterized by the presence of primitive or atypical myeloid or lymphoid cells in the bone marrow and the blood. "It is interesting that both the patients with LMNB1::PPP2R2B fusion carried ETV6::RUNX1 fusion, implying that LMNB1::PPP2R2B fusion played a role in the pathogenesis of ETV6::RUNX1-positive leukemia." (PMID 36612032, 2022).
liver fibrosis (1 paper, 2025). "In contrast, Ppp2r2b, Sgpp2 (P < 0.0001), and Oprd1 (P < 0.001) were significantly upregulated in the WD liver fibrosis model." (PMID 40557038, 2025).
medulloblastoma (1 paper, 2016). A malignant, invasive embryonal neoplasm arising from the cerebellum. "An intriguing observation concerns the fact that three genes in Set A whose expression is significantly modified - namely, Nlk, Raf1, and Ppp2r2b—are markers for group 3 medulloblastoma." (PMID 27965576, 2016).
metastatic tumors (1 paper, 2020). "PPP2R2B expression showed marked downregulation in the relapsed metastatic tumors compared to the primary tumors (P = 0.0035), suggesting a correlation between PPP2R2B downregulation and trastuzumab resistance." (PMID 33208750, 2020).
neuroblastoma (1 paper, 2009). Neuroblastoma (NB) is the most common solid, extracranial childhood tumor. "Human neuroblastoma cells were transfected with PPP2R2B constructs encoding the complete sequences of Bβ2 and Bβ1, respectively." (PMID 20017961, 2009).
oral squamous cell carcinoma (1 paper, 2015). "The methylation of DACH1, DKK1, LKB1, PPP2R2B, RUNX3, SFRP2, and WIF-1 was analyzed in 16 oral squamous cell carcinoma cell lines using the methylation-specific polymerase chain reaction." (PMID 25487617, 2015). "In the first stage, 16 oral squamous cell carcinoma cell lines were screened for the methylation of DACH1, DKK1, LKB1, PPP2R2B, RUNX3, SFRP2, and WIF-1 using methylation-specific PCR." (PMID 25487617, 2015).
Schinzel-Giedion syndrome (1 paper, 2016). Schinzel-Giedion syndrome (SGS) is an ectodermal dysplasia syndrome chiefly characterized by a distinctive facial dysmorphism, hydronephrosis, severe developmental delay, typical skeletal malformations, and genital and cardiac anomalies. "On the blood side of this signature were among others the PPP2R2B gene associated with SCA12, CAPNS2, which was recently found to play a beneficial role against polyglutamine toxicity, and SETBP1 which is associated with the Schinzel-Giedion syndrome." (PMID 27476530, 2016).
tumor (16 papers, 2010 to 2025). "Promoter methylation of PPP2R2B in the pre-treatment sample was significantly associated with tumour grade (p = 0.019), whereby high-grade tumours were more frequently unmethylated than grade 1 and 2 tumours in the discovery cohort." (PMID 20338046, 2010). "To clarify the association between PPP2R2B expression and tumor immune response, we performed GSVA." (PMID 33407498, 2021). "Consistent with the data from our in vitro assays, tumor volume and weight were decreased in the PPP2R2B overexpression group compared with the control group." (PMID 38976080, 2024). "Then, we performed RT-PCR using our cohort and the results further confirmed that the expression of PPP2R2B was distinctly decreased in BC specimens compared with non-tumor specimens." (PMID 38409085, 2024). "Meanwhile, PPP2R2B overexpression dramatically enhanced the efficacy of cisplatin in vivo, evidenced by a more prominent reduction in tumor volume and weight than that observed in the empty vector plus cisplatin group." (PMID 38976080, 2024). "Next, we detected PPP2R2B expression levels in BC and adjacent non-tumor tissues using RT-qPCR, western blot and immunohistochemistry (IHC)." (PMID 38976080, 2024). "After identifying the functions of PPP2R2B in inhibiting tumor growth and metastasis, further bioinformatics analysis was performed to explore the possible other functions of this protein." (PMID 38976080, 2024). "In the pan-cancer analysis, PPP2R2B expression emerged as a potential indicator of clinical stages and grade in several tumor types." (PMID 38409085, 2024). "Enzyme substrate specificity is conferred by the B subunits of PP2A proteins, among which PPP2R2B is a B55 subunit whose inactivation promotes tumor progression and mediates development of tumor drug resistance." (PMID 38976080, 2024). "In this study, we identified PPP2R2B as a robust tumor suppressor in TNBC by systemic bioinformatics analyses." (PMID 33407498, 2021). "In this study, we performed systematic bioinformatics analyses to identify PPP2R2B as a robust tumor suppressor in TNBC." (PMID 33407498, 2021). "This study provided a basis for the understanding of the complex interaction between PPP2R2B and tumor immunity." (PMID 33407498, 2021). "PPP2R2B is a candidate tumor suppressor gene and it was shown that changes in DNA methylation of this gene contribute to its expression." (PMID 24093668, 2013). "Finally, as PPP2R2B is a tumor suppressor, which is difficult to overexpress as a possible therapeutic target, we searched for an upstream mechanism that negatively regulates PPP2R2B." (PMID 38976080, 2024). "To test our hypothesis that PPP2R2B functions as a tumor suppressor gene, we first performed a series of in vitro experiments." (PMID 38976080, 2024). "In summary, as a SUV39H1-specific inhibitor, chaetocin may suppress tumor growth and increase the sensitivity of BC cells to cisplatin by up-regulating PPP2R2B expression." (PMID 38976080, 2024). "As PPP2R2B is a tumor suppressor, upstream activation of its expression is feasible." (PMID 38976080, 2024). "In general, PPP2R2B was lower in tumor samples than those in paired adjacent tissue." (PMID 38976080, 2024). "Finally, PPP2R2B was identified as a hub tumor suppressor that was frequently downregulated in TNBC tissues compared with normal breast tissues." (PMID 33407498, 2021).
tumor (continued). "Evidences sourced from the genome, transcriptome, and in vitro experiments supported that PPP2R2B downregulation could help TNBC cells to evade immune surveillance via suppressing anti-tumor immune response." (PMID 33407498, 2021). "In our study, the gene ontology analysis of biological functions was performed to identify that PPP2R2B could play a crucial role in tumor immune response." (PMID 33407498, 2021). "In univariate analysis, larger tumour size, with pharmaceutical drug adjuvant therapy, high FNCLCC grade, increased COL11A1, ITGA10 and KIF26B expression, and decreased CLEC3B, DUOX2, KRT75 and PPP2R2B were risk factors of shorter RFS." (PMID 31742892, 2020). "In summary, PPP2R2B may have an important role as a tumor suppressor in BC." (PMID 38976080, 2024). "Besides, we observed most genes associated with antigen presentation were activated in high expression group of PPP2R2B.These findings suggested that PPP2R2B downregulation was also likely to contribute to tumor immune evasion through suppressing antigen presentation pathway." (PMID 33407498, 2021). "Based on the results of pan-cancer analysis, we found that GLRX2, NMT1, PPP2R2B and TRAF3IP3 exhibited a dysregulated level in many types of tumors, highlighting their potential roles in tumor progression." (PMID 38409085, 2024). "The levels of PPP2R2A, PPP2R2B, and PPP2R2D genes expression in tumor tissues of HCC patients from the GEO (GSE76427) and TCGA-LIHC dataset were lower than those in peritumor tissues." (PMID 37554285, 2023). "The tumor suppressive partners comprise three highly significant binding components: MIR99AHGlncRNA/PIK3R3, miR-661/ZYG11A, and PPP2R2B/ZNF136 (Supplementary Excel Files S4 and S5)." (PMID 36289596, 2022). "Promoter methylation analysis revealed that PPP2R2B, and to some extent PPP2R3A and PPP2R5A are the only subunits predominantly methylated across multiple tumor types." (PMID 27557495, 2016). "The eight genes displaying variable DNA methylation patterns in a significant number of tumours (ABCB1, BRCA1, CDKN2A, FOXC1, GSTP1, IGF2, PPP2R2B and PTEN) within the discovery cohort were tested for association with survival by a logrank test." (PMID 20338046, 2010). "PPP2R2B is a regulatory subunit of a PP2A heterotrimeric complex, which has a role in recognizing dephosphorylated substrates, including cyclin E1 and PDK1, which participate in the cell cycle and tumor proliferation." (PMID 38976080, 2024). "Additionally, breakpoints in PPP2R2B, a component of the regulatory subunit B of serine/threonine phosphatase 2 (PP2A) involved in cell growth and division, were found in two samples (one serous and one clear cell tumour)." (PMID 22514011, 2012). "There was a trend for the absence of methylation at ABCB1, FOXC1, PPP2R2B, and GSTP1 in both the basal-like and normal-like tumours, while IGF2, MLH1 and PTEN were hypomethylated in the basal-like tumours but not in the normal-like tumours." (PMID 20338046, 2010).
cancer (14 papers, 2010 to 2026). A tumor composed of atypical neoplastic, often pleomorphic cells that invade other tissues. "On the gene locus of PPP2R2B, a known cancer-associated gene, the peaks were decreased, suggesting reduced chromatin accessibility." (PMID 40181449, 2025). "Among them, a few have been previously implicated in modulating drug sensitivity in other cancer types, including PPP2R2B, PPP2R2A, PPP2R5A, and PPP2R1A24,31,37." (PMID 33208750, 2020). "Decreased expression of PPP2R2B has been linked with the promotion of deregulated oncogene signaling pathways required for survival and proliferation of cancer cells, suggesting the different cell proliferation rates between mild and moderate WS." (PMID 32612536, 2020). "RNA-Seq data from TCGA BLCA cohort revealed that PPP2R2B expression was significantly down-regulated in cancer tissues." (PMID 38976080, 2024). "Since immunotherapy associated with immune checkpoints have provided clinical benefits for several patients with cancer, we analyzed the relationship between PPP2R2B expression and immune checkpoints family members." (PMID 33407498, 2021). "FBP1 was significantly associated with overall survival outcomes in 10 cancers while PPP2R2C and PPP2R2B in 8 cancers." (PMID 32807122, 2020). "PPP2R5B and PPP2R2B belong to the protein phosphatase 2A family, which is implicated in the negative regulation of AKT protein, and consequently reduces cancer cell growth and division." (PMID 28114404, 2017). "Therefore, the epigenetic mechanism of PPP2R2B silencing appears to be cancer type-dependent, highlighting the need for different epigenetic compounds to activate PPP2R2B expression in different cancer types." (PMID 33208750, 2020). "Compared to parental cells, BEZ235-resistant cells displayed promoter hypermethylation of the tumor suppressor genes PTEN and PPP2R2B, suggesting that methylation of these genes may function to promote cancer proliferation." (PMID 25762617, 2015). "We suggest that persistent residual signaling of both p70S6K and 4EBP1 following anti-HER2 treatment in low PPP2R2B-expressing cancer cells might collaterally confer treatment failure, though its correlation with clinical resistance to anti-HER2 therapy needs futher validated in clinical samples." (PMID 33208750, 2020). "Meanwhile, the amplification peaks of cancer suppressors containing NF1 and MAP2K4 were detected in patients with high level of PPP2R2B expression." (PMID 33407498, 2021). "DNA methyltransferases were upregulated and induced PTEN and PPP2R2B gene hypermethylation, which downregulated their expression in BEZ235-resistant cancer cells." (PMID 25762617, 2015). "In this study, we demonstrated that DNA methyltransferase is a key modulator that can induce PTEN and PPP2R2B gene hypermethylation, leading to the downregulation of their expression in BEZ235-resistant cancer cells." (PMID 25762617, 2015).
neurological disorders (3 papers, 2022 to 2024). "Intriguingly, both PPP2R2B and PPP2R2C have been associated to neurological disorders." (PMID 38331954, 2024).
cardiovascular disease (1 paper, 2012). "Using this approach, we have identified four candidate genes (EBF1, PPP2R2B, PRELID2, and SPOCK1) that may represent novel cardiovascular disease risk genes mediated through LDL cholesterol pathways." (PMID 22369142, 2012).
inflammation (1 paper, 2025). Aberrant reaction of the microcirculation characterized by movement of fluid and leukocytes from the blood into extravascular tissues. "The PPP2R2B gene, located on chromosome 5 (5q32), has been reported to protect against organ damage caused by activated T cells in chronic inflammation and systemic autoimmune diseases." (PMID 39851522, 2025).
neurodegenerative disease (1 paper, 2021). A disorder of the central nervous system characterized by gradual and progressive loss of neural tissue and neurologic function. "In B cells, the upregulated genes KIR3DL2, QPCT, and PPP2R2B are all involved in neural function and neurodegenerative diseases, and the downregulated genes FRAT2 and WWC3 are involved in the Wnt/β-Catenin signaling pathway, which is associated with AD pathogenesis." (PMID 34880454, 2021). "In addition, differentially expressed genes in B cells were identified; both the upregulated genes (KIR3DL2, QPCT, PPP2R2B) and the downregulated genes (FRAT2, WWC3, SPG20) had certain connections with neurodegenerative diseases." (PMID 34880454, 2021).
neurodevelopmental disorder (1 paper, 2025). A behavioral and cognitive disorder with onset during the developmental period that involves impaired or aberrant development of intellectual, motor, or social functions. "In the present study, we newly identify four individuals with a neurodevelopmental disorder (NDD) and with monoallelic PPP2R2B variants (three confirmed de novo)." (PMID 39565297, 2025).